ATR (ATR checkpoint kinase)
Diseases named in the same sentence as ATR in open-access papers (continued):
Sharing a sentence is not in itself a finding about the gene and the disease.
tumor (continued). "Taking advantage of our multi-omics studies, we further elucidated the mechanism by which PRKDC might promote tumor cell proliferation through its cis-effect and collaborate with ATM and ATR." (PMID 39039072, 2024). "Previously, we have shown that ATR inhibition using ceralasertib improves the radiation response in preclinical models of NSCLC by enhancing tumour efficacy with no significant impact on radiation fibrosis." (PMID 39063060, 2024). "To assess whether ATR inhibition enhanced the systemic antitumor effect of combined ICI therapy and ablative radiotherapy, we used a synchronous LLC lung and flank tumor mouse model." (PMID 39487895, 2024). "To investigate whether the adaptive antitumor immunity potentiated by combined ATR inhibition and ablative radiotherapy enhanced systemic immunotherapy responses in vivo, we established a synchronous LLC lung and flank tumor mouse model." (PMID 39487895, 2024). "Moreover, increased levels of KRAS, ATR, and CHEK proteins correlated with a high rate of tumor cell proliferation and aneuploidy in ECE cases with metastatic lesions following primary tumor resection." (PMID 38669256, 2024). "In CT 26 and MC38 mice models, ceralasertib, a potent ATR inhibitor, showed no direct effects on tumor killing, which is typical for this class of agents." (PMID 39100682, 2024). "Accordingly, ATR or CHK1 inhibition decreases PD-L1 expression and may facilitate the T-cell-mediated killing of the tumor cell, which may be of particular interest in UCOGC characterized by frequent PD-L1 expression." (PMID 38542259, 2024). "Furthermore, the combinations of ATR and TOP1 inhibitors can augment tumor inflammation in STING‐low SCLC." (PMID 35957613, 2023). "This requires more investigative work comparing these various radiation modalities in combination with inhibitors such as those targeting PARP, ATM, ATR, DNA-PKcs and CHK1, to confidently determine a specific strategy that is efficacious in radiosensitising specific tumours." (PMID 37695845, 2023). "To identify previously unknown tumor‐suppressive pathways involved in the DDR, we interrogated a catalog of BCL driver genes and a dataset of ATM and ATR substrates." (PMID 37485814, 2023). "Elimusertib (BAY1895344) is a novel ATR inhibitor that produced powerful efficacy as monotherapy and synergistic antitumor activity when combined with radiotherapy, chemotherapy, or other DDR inhibitors in tumor xenograft models." (PMID 37109350, 2023). "Our data suggests that drugs targeting DNA repair, such as PARP or ATR inhibitors, may induce apoptosis preferentially in EHE tumour cells through synthetic lethality." (PMID 37980390, 2023). "Of note, while the initial DNA lesions sensed by ATM or ATR are diverse, downstream signaling cascades are to some extent overlapping and, hence, the integration of ATM and ATR as well as the cell cycle and tumor cell signaling status will influence the net outcome of the DDR." (PMID 37041372, 2023). "The results of this study, by demonstrating clear divergences in the impact of dysregulation of ATM, ATR, and CHK2 on important tumor characteristics, shed new insight into how early decisions to turn off cell cycle regulation can direct the course of ensuing disease." (PMID 37390209, 2023). "Normal tissues, such as bone marrow and intestinal epithelium, were not harmed in these mice, showing the tumor selectivity potential of ATR inhibition." (PMID 37511442, 2023). "ATR inhibitors have shown anti-tumor effectiveness, not just as monotherapies but also in enhancing the effects of standard chemotherapy, radiation, and immunotherapy." (PMID 37511442, 2023). "ATM/ATR-mutated patients had significantly higher tumor mutational burdens (TMB; P < 0.001) and microsatellite instabilities (MSI; P = 0.023), but not chromosomal instabilities, than those without any ATM/ATR variations." (PMID 38041093, 2023).
tumor (continued). "Finally, targeting the ATR pathway, genetically or pharmacologically, re-sensitised resistant cells to MTX in vitro and potently prevented the growth of MTX-R tumours in vivo." (PMID 35301407, 2022). "Our western blotting experiment showed that ERK signaling as well as ATM/ATR signaling was attenuated by the downregulation of hnRNP G‐T and ZDHHC11, supporting that the hnRNP G‐T‐ZDHHC11 pathway promoted tumor progression, which mediated the ATM/ATR signaling pathway." (PMID 35384384, 2022). "Combined inhibition of ATR and PARP, an enzyme involved in the stabilization of replication forks, resulted in a significant reduction of resistance to radiation in both GSC and tumor bulk populations." (PMID 35158967, 2022). "In addition, experiments demonstrated that VE-821 can inhibit ATR-mediated signaling under hypoxia, thereby inhibiting the stability of HIF-1α and increasing the sensitivity of tumor cells to radiotherapy." (PMID 36139386, 2022). "In addition to T/NK cells, the expression level of ATR in immune cells (myeloid cells, B lymphocytes, MAST cells) of tumor patients is higher." (PMID 35712480, 2022). "Although DNA repair genes alterations and the resulting genomic instability have been explored in other tumor types, only few DDR inhibitors were employed as monotherapy or combined with chemotherapy in trials enrolling CRC patients, including PARP, WEE1, ATR, and CHK1 inhibitors." (PMID 34201502, 2021). "In addition, ARID1A loss sensitizes cancer cells to PARP inhibitors potentially via inhibition of ATR function in DSB repair, suggesting a new method of targeting tumor cell synthesis to lethality." (PMID 34671561, 2021). "While we observed only mild synergy when combining ATR and ALK inhibition, we rationalised that combination with lorlatinib, which has previously been shown to reduce tumour growth in ALK-driven NB mouse models, may improve treatment responses." (PMID 34819497, 2021). "The rapid tumour shrinkage in response to ATR inhibition with BAY 1895344 was accompanied by an inflammatory signature and extensive immune infiltration of tumours, implying that ATR inhibition does not negatively impair the immune response." (PMID 34819497, 2021). "In addition, the phosphorylation expression levels of PI3K, AKT, ATR and ATM decreased in the combination therapy compared with monotherapy or vehicle in subcutaneous tumours." (PMID 34761497, 2021). "Most of these studies have so far focused on the targeting of the ATR/CHK1 pathway, with the idea that latent RS in MYC-dependent tumor cells might constantly engage ATR/CHK1 to prevent rampant genomic instability." (PMID 34201047, 2021). "The robust inhibition of NB cell lines by ATR inhibition was confirmed in a xenograft NB model, where BAY 1895344 monotherapy treatment was as effective as the third-generation ALK TKI lorlatinib in reducing tumour growth." (PMID 34819497, 2021). "ATR, ATM and DNA-PK inhibition may also increase MHC-I expression in tumor cells to effect antigen presentation and T cell infiltration." (PMID 34298632, 2021). "A timed paired tumor biopsy study with the M6620-carboplatin combination supports preclinical data indicating that delayed administration of M6620 is appropriate and that the RP2D is sufficient to inhibit ATR activity in tumors." (PMID 32568634, 2020). "Taken together, this study reports that replication stress induced by overexpression of Cyclin E1 and Cdc25A results in the formation of lagging chromosomes and chromatin bridges, which is further exacerbated by inhibition of ATR or WEE1 kinases, and results in exacerbated tumor cell killing." (PMID 33028815, 2020). "Conversely, ATR’s functions in regulating G2-M checkpoint activation, replication fork stability and late-origin firing appear to dominate ATR-inhibitor efficacy, with ATR and WEE1 inhibitors showing efficacy in tumours with high replication stress." (PMID 32444694, 2020).
tumor (continued). "Candidate pathogenic mutations in untranslated regions (UTRs) and BC-relevant genes regions, including oncogenes (i.e., KRAS, ERBB3, PIK3C2G) and tumor suppressor genes (i.e., FANCC, ATR, SMAD2), were found in organoids, and the majority of them were conserved within the tumor–organoid pair." (PMID 33371412, 2020). "To extend our in vitro data we next used a murine xenograft tumor model to assess the sensitivity of POLD1+/+ and POLD1R689W/- cells to the ATR inhibitor AZD6738 in vivo, as this inhibitor showed the strongest proliferation inhibitory effects in the in vitro experiments." (PMID 33144657, 2020). "Tumor cells that have persistent replication stress are unable to activate the ATR/CHK1 checkpoint response in the absence of FACT." (PMID 32533099, 2020). "Another limitation of this study is that only one ACC PDX-model was tested and that ATR inhibition did not result in tumor regression in more than one mouse." (PMID 32001675, 2020). "Interestingly, Genufu subtype (ER+/HER-2−/low proliferation), Her-2+, PAM50.Her-2 subtype and PAM50.Luminal A subtype were more common in tumours with low MYC mRNA and low ATR mRNA expressions (all adjusted p values ≤ 0.01)." (PMID 30746633, 2019). "Indeed, ATR and CHK1 haplo-insufficiencies enhance oncogene-induced tumor formation, but a more severe depletion of ATR is synthetic lethal with oncogene overexpression." (PMID 30796221, 2019). "The effect of gender on the expression of the studied genes revealed that for ATR females had two-fold higher expression compared to males, whereas POT1 was expressed at a significantly higher level in the tumor tissue relative to adjacent mucosa only in the male patients." (PMID 29870526, 2018). "ATR and/or pCHK1ser345 did not influence survival in tumours with low- or high-cytoplasmic PTEN expression." (PMID 29396668, 2018). "Importantly, ATR and CHEK1 expression were both inhibited in the tumor tissues of miR-126 overexpression group mice." (PMID 30315225, 2018). "Mounting evidence suggests that ATR/CHK1 pathway, frequently upregulated in human neoplasm, may promote tumor growth." (PMID 30315225, 2018). "We have clearly shown that ATR has non-cell-autonomous tumor suppressive functions both in vitro and in animal models." (PMID 30410668, 2018). "Overall these studies suggest that ATR/CHK1 inhibition triggers tumor cell death but it has not been addressed by what mechanism these cells die32." (PMID 29167438, 2017). "However, in response to IR, some tumor cells activate DSBs repair and pro-survival pathways such as EGFR/ATM/ATR/BRCA1/Chk1 and PI3K/Akt or RAS/Raf/ERK1/2, rendering them radio-resistant." (PMID 28423495, 2017). "Finally, a combination of ATR inhibitor (AZD6738) and PARP inhibitor (olaparib) was tolerated in vivo through intermittent doses and showed significant anti-tumour efficacy in multiple human patient derived primary explant models." (PMID 28448462, 2017).
tumor (continued). "Both ATR and DNA-PKcs expression was higher than ATM in all tumour classifications." (PMID 27527858, 2016). "Skeletal muscle that had been infiltrated by tumour cells was mainly negative for ATM/ATR but some staining was seen for DNA-PKcs (data not shown)." (PMID 27527858, 2016). "Determining whether non-replicating cells are equally sensitized to ETs by dual inhibition of ATR and ATM than actively replicating tumor cells might be part of the answer." (PMID 27029031, 2016). "We hypothesized that up-regulation of DNA damage response genes such as ERH, ATR and CHK1 in HCC tumor cells could contribute toward resistance to DNA-damaging chemotherapy and inhibiting DNA damage response might thus overcome this resistance." (PMID 25880358, 2015). "Our results show that indeed Ajuba is also important in non-tumor cells to repress the ATR response in absence of exogenous DNA damage." (PMID 23755068, 2013). "We conclude that depletion of Ajuba in IMR90 leads to a qualitatively similar response to our tumor cell system HTC75, which corresponds to ATR activation, but with a different outcome regarding the nature of the cell cycle profile (G2/M delay in IMR90 versus S-phase delay in HTC75)." (PMID 23755068, 2013). "Indeed, while ATM activity constitutes a barrier to malignant transformation, full activation of ATR and CHK1 is essential for tumor maintenance, providing important opportunities for therapeutic intervention." (PMID 22373487, 2012). "Selected CRC target genes involved in apoptosis (BAX), tumor growth (TGFβRII), WNT pathway (AXIN2, TCF4, WISP3), DNA repair (ATM, ATR, BLM, BRCA1, BRCA2, DNAPKcs, MBD4, MRE11, MSH3, MSH6, RAD50, XRCC2) and PI3-kinase signaling (PTEN) were analyzed for mutations in MSI-positive HGG samples." (PMID 21637783, 2011). "Tumour cell lines depleted of ATR showed a similar apoptotic response to replication inhibitors as the same cells depleted of Chk1 and co-depletion of ATR and Chk1 had no further effect." (PMID 20813042, 2010). "Our data suggest that it plays little or no role in tumour cell lines in response to DNA replication fork stress relative to the ATR-Chk1 pathway." (PMID 19119425, 2009). "Acute DDR blockade—such as short-term PARP or ATR inhibition—induces rapid accumulation of cytosolic DNA, robust cGAS–STING activation, type I interferon release, and increased antigen presentation, thereby creating a transient window of heightened tumor immunogenicity." (PMID 41373427, 2025). "However, more findings support the idea that the tumor-suppressing effects of ATR inhibitors are independent of the ALT mechanism, indicating that other targets need to be explored." (PMID 40025590, 2025). "When defects occur in the ATM/ATR signaling pathway, both ATM‐mediated HRR and NHEJ repair pathways fail to activate properly, resulting in decreased DSBs repair efficiency, accumulation of intracellular DNA damage, and ultimately increased tumor cell sensitivity to chemotherapeutic agents." (PMID 41473689, 2025). "This pathway has been confirmed in both genotoxic stress and radiotherapy models, where activation of ATM/ATR signaling increases PD-L1 expression via IRF1, contributing to attenuation of IFN-driven T-cell responses and promoting short-term survival of stressed tumor cells." (PMID 41373427, 2025). "This meta-analysis, which included 8 randomized controlled trials and 2 non-randomized comparative studies involving 810 patients, showed that when all tumor types were pooled, ATR inhibitors did not significantly improve key efficacy outcomes compared with conventional therapies." (PMID 41409249, 2025). "Beyond its canonical role in DDR and genomic stability, ATR also participates in multiple non-nuclear cellular processes that contribute to tumor survival, such as regulating mitochondrial bioenergetics, maintaining cytoskeletal integrity, and modulating metabolic flux." (PMID 41409249, 2025).
tumor (continued). "Notably, no new mutations were detected in the target gene ATR, its downstream effector CHK1, or any other DDR/DNA repair gene beyond those already identified in the parental tumor tissues." (PMID 41387887, 2025). "ATR inhibition leads to the accumulation of cytosolic DNA fragments that activate the cyclic GMP-AMP synthase-stimulator of interferon genes (cGAS-STING) pathway, a key sensor of DNA damage that stimulates type I interferon signaling and promotes immune-mediated tumor clearance." (PMID 40869030, 2025). "Given that SLFN11 impairs DNA repair by inhibiting the translation of key DDR genes such as ATR, it is theoretically possible that tumor cells with low SLFN11 expression may be more dependent on residual ATR pathway activity for survival, making them particularly sensitive to ATR inhibitors." (PMID 40766331, 2025). "To elucidate the differences in KRAS, ATR, CHEK1 mRNA expression levels between the two analyzed group of samples, we checked for their correlation with tumor grade differentiation and depth of myometrium invasion, which are key clinicopathological indicators of tumor progression." (PMID 38669256, 2024). "Therefore, a certain level of ATR expression appears to be necessary to reduce DNA damage to non-lethal levels and allow tumor cell growth under oncogenic RAS-induced RS." (PMID 39456601, 2024). "In addition, the authors highlighted the synergistic effects of oxaliplatin and the ATR inhibitor VE-822 in many colorectal cancer cell lines, demonstrating the occurrence of cytosolic DNA release, CD8 + T cell infiltration and reduced tumour growth in immune competent mice." (PMID 39271762, 2024). "None of the CGH probes show evidence of deletion at ATR locus in the tumor DNA of PED2361.1." (PMID 36749285, 2023). "However, increased expression of ATR and ATM proteins was observed in insensitive tumor cells." (PMID 37305685, 2023). "Furthermore, the same low, single dose of PEG-Exa administered with the ATR inhibitor VX970 at doses of the DNA damage response inhibitor that do not affect tumor growth show high tumor regression, strong synergy, and synthetic lethality." (PMID 37377899, 2023). "Thus, the inhibition of the ATR signaling cascade specifically sensitizes BCSC to irradiation and increases the activation of the intracellular immune response, potentially overcoming CSC-mediated tumor protection." (PMID 35280989, 2022). "In addition, conditions that activate ATM and ATR as part of DDR may also participate in regulating the innate immune system and alert it to potentially ‘dangerous’ tumour cells." (PMID 36106115, 2022). "Thus, MYCN does not seem to contribute to ATR inhibitor sensitivity in ARMS to the same extend as it does in other tumor entities." (PMID 35879366, 2022). "ATR inhibition also impairs cell cycle progression and selective ATR inhibitors, including ceralasertib (AZD6738) and berzosertib (M6620/VX-970/VE-822), have shown anti-tumor activity both as single agents or in combination with DNA-damaging chemotherapy, irradiation, and PARP inhibitors." (PMID 35052761, 2021). "This may mean that identified hits do not fully reflect the drivers of cell death in tumours harbouring specific genetic defects, such as mutations in ATM, that are likely to be targeted with ATR inhibitors in the clinic." (PMID 34329458, 2021). "Although we tried to ensure mechanistically that J54 works via inhibition of the ADT-activated TLK > Nek1>ATR > Chk1 DDR pathway, we cannot rule out that the tumor regression effects that we have observed could be caused by inhibition of some other target." (PMID 32905878, 2020). "Whilst the majority of these studies have focused on utilising clonogenic assays as an end-point, the ATR inhibitor AZD6738 was shown to impede the growth of 3D spheroids of hypopharyngeal (FaDu) cells in combination with radiation, which are more representative of the original tumour in vivo." (PMID 32517381, 2020).